DEPDC1 (DEP domain containing 1)
Diseases named in the same sentence as DEPDC1 in open-access papers (continued):
Sharing a sentence is not in itself a finding about the gene and the disease.
tumor (continued). "Few studies have shown that DEPDC1 regulates tumor proliferation and metastasis via Wnt/β-catenin signaling pathway." (PMID 34268303, 2021). "Previous studies report overexpression of DEPDC1 in several tumors and reported that it drives tumor pathogenesis through multiple potential mechanisms." (PMID 34556750, 2021). "The results showed that the mRNA expression levels of hub genes (PBK, KIF2C, NUF2, KIF20A, RAD51AP1 and DEPDC1) in tumor samples (EAC, ESCC) were significantly higher than in normal samples (P < 0.05)." (PMID 33403046, 2021). "An important paralog of this gene is DEPDC1, and it is overexpressed in the case of tumor progression." (PMID 32193399, 2020). "By inhibiting the expression of DEPDC1, it can inhibit tumor cell growth and promote cell apoptosis." (PMID 33140894, 2020). "DEPDC1 expression level was significantly enhanced in tumor stages compared with normal breast tissues." (PMID 31032225, 2019). "Six genes (67%) tended to be highly expressed in POLE-category tumours, with DEPDC1 and TTK genes in particular exhibiting significant differences in expression." (PMID 29880869, 2018). "At the end of the study (day 30), tumor weight and tumor size of DEPDC1 knockdown group (0.23±0.03g, 46.91±15.07mm3) was only 41.1% and 8.6% of the control group (0.56±0.17g, 546.24±93.46mm3)." (PMID 28969015, 2017). "GSEA confirmed that DEPDC1 was involved in gene expression and tumor-related signaling pathways." (PMID 38564630, 2024). "DEP domain‐containing 1 (DEPDC1) is a newly identified tumor‐related gene." (PMID 36479633, 2023). "DEPDC1 is a newly discovered tumor‐related gene that has a highly conserved domain." (PMID 36479633, 2023). "Notably, H&E staining illustrates multi‐focal necrotic areas with cell nuclear condensations and cytoplasmic fibrosis on DEPDC1‐knockdown tumor sections." (PMID 36479633, 2023). "Together, these results show that DEPDC1 stimulated tumour development by FOXM1 regulation." (PMID 36072787, 2022). "In conclusion, our study highlighted that eL31 may work as a tumor promotor in CRC via targeting DEPDC1." (PMID 36309731, 2022). "Furthermore, in line with eL31’s expression in CRC, IHC analysis also revealed DEPDC1 upregulation in CRC tumor tissues." (PMID 36309731, 2022). "In addition, in normal tissue, HNSC and TCGA RNA sequencing data showed through GEPIA2 and UALCAN analysis that expression of DEPDC1 is upregulated in tumour tissues compared to normal tissue, whereas stages were significantly associated with DEPC1 expression." (PMID 36072787, 2022). "A recent study has suggested that DEPDC1 may regulate tumor proliferation and metastasis via Wnt/β-catenin signaling pathway in HCC." (PMID 34268303, 2021). "qPCR assays also confirmed that DEPDC1 was up-regulation in 127 NSCLC tumor tissues." (PMID 32396871, 2020). "By IHC, we observed that the staining of DEPDC1 was in nucleus of CRC tumor cells." (PMID 33140894, 2020). "In summary, with the deepening of research on DEPDC1, it has been found that it plays a significant role in the growth and progression of a variety of malignancies and is expected to become one of the new targets for tumor therapy." (PMID 33140894, 2020). "We used Kaplan‐Meier Plotter (kmplot.com) to analyse the correlation between the tumour DEPDC1 expression levels and the overall survival (OS), first progression (FP) and post‐progression survival (PPS) of LUAD patients (N = 720) in this database with auto select best cut‐off." (PMID 33021072, 2020). "Overall, our findings imply that STAT1-induced upregulation of KTN1-AS1 display tumor-promotive roles in NSCLC progression via regulating miR-23b/DEPDC1 axis, suggesting that KTN1-AS1 may be a novel biomarker and therapeutic target for NSCLC patients." (PMID 32396871, 2020).
tumor (continued). "By IHC, we examined the protein expression of DEPDC1 in 150 CRC tissues and ANCTs and observed that the staining of DEPDC1 was in nucleus of tumor cells, and the proportion of DEPDC1 high expression was significantly greater in CRC compared to that in ANCTs (P = .019)." (PMID 33140894, 2020). "DEPDC1 was significantly enhanced in tumor tissues compared with matched normal tissues." (PMID 31032225, 2019). "Thus, it is worthwhile to further investigate the functional implication of DEPDC1-mediated activation of NF-κB pathway in tumor-derived inflammation as well as NPC development." (PMID 28969015, 2017). "Knockdown of DEPDC1 also significantly inhibits tumor growth in vivo." (PMID 28969015, 2017). "Importantly, in BALB/c mice’s model, MEETL5 overexpression-induced tumor progression could be partially abrogated by DEPDC1 knockdown." (PMID 40018408, 2025). "However, in previous studies, DEPDC1 has been little studied in tumor glycolysis." (PMID 39068164, 2024). "MiR-26b functioned as a negative regulator of DEPDC1 in TNBC cells and also FOXM1 enhanced stimulating effects of DEPDC1 on tumor growth." (PMID 37689738, 2023). "Mechanistic examination showed that restored DEPDC1 expression in vivo and in vitro stimulated OSCC tumour development." (PMID 36072787, 2022). "Our findings showed that levels of expression of DEPDC1 protein and mRNA in OSCC tissue were considerably increased, and a progressive improvement in the tumour stage was recorded." (PMID 36072787, 2022). "Xenograft experiments frequently indicated that the consequences of over-expressing DEPDC1 were rescued by suppressing FOXM1 levels, resulting in the reduced progression of tumours." (PMID 36072787, 2022). "In the five-gene signatures in the ceRNA network, the expression levels of DEPDC1, CPS1, COL9A3, and PTPN21 were significantly different between early- and advanced-stage tumor tissues." (PMID 34855841, 2021). "The results indicated that tumor purity significantly and positively correlated with PBK (R= 0.24, P= 1.13e-03), NUF2 (R= 0.267, P= 2.75e-04), RAD51AP1 (R= 0.275, P= 1.83e-04), and DEPDC1 (R= 0.166, P= 2.56e-02) expression." (PMID 33403046, 2021). "Strong staining of DEPDC1 protein was detected in 26 (59%) of 44 NPC, but only in 7 (27%) of 26 non-tumor tissues." (PMID 28969015, 2017). "Our results showed that DEPDC1 was overexpressed at both mRNA and protein levels in NPC tissues compared with normal or non-tumor tissues." (PMID 28969015, 2017). "Additionally, DEP domain containing 1 (DEPDC1) promotes glycolysis in RCC via the AKT/mTOR/HIF1α pathway, which in turn affects tumor metastasis and TKI resistance." (PMID 39901876, 2025). "For example, DEPDC1 has been shown to activate NF-κB and E2F signaling pathways to accelerate cell cycle progression, and to promote the K-RAS and Wnt/β-catenin signaling pathways to drive tumor cell proliferation and metastasis." (PMID 34268303, 2021). "However, the specific molecular mechanism through which DEPDC1 enhances tumor glycolysis had not yet been fully elucidated." (PMID 39068164, 2024). "However, there is no existing drug targeted to DEPDC1 for the treatment and prevention of tumor metastasis." (PMID 34268303, 2021). "We detected the expression of all five CPV antigens in post-vaccination tumor tissue, with the exception of one participant without URLC10 expression and one participant with an unevaluable sample for DEPDC1 staining." (PMID 32500232, 2020).
DEPDC1 also shares sentences with these, for which no sentence is quoted: hepatitis B (2 papers); invasive ductal carcinoma (2); lung squamous cell carcinoma (2); adenocarcinoma (1); anaplastic thyroid carcinoma (1); endometrial endometrioid carcinoma (1); Fanconi anemia (1); glioblastoma (1); head and neck squamous cell carcinoma (1); malignant glioma (1); meningioma (1); pancreatic cancer (1); soft tissue sarcoma (1).